CXCL8 (C-X-C motif chemokine ligand 8)
Diseases named in the same sentence as CXCL8 in open-access papers (continued):
Sharing a sentence is not in itself a finding about the gene and the disease.
infection (continued). "qRT-PCR revealed that upon T. marneffei infection, mRNA expressions of TNF and CXCL8 were only significantly stimulated in hPBDMs when cultured with the supplementation of autologous plasma during the course of infection." (PMID 37695039, 2023). "Chemokine CXCL8 is a key facilitator of the human host immune response, mediating neutrophil migration, and activation at the site of infection and injury." (PMID 36622452, 2023). "The RNASeq analyses of MDMs were validated using quantitative RTPCR based on CCL19, highly induced in the presence of hSAA-1, CSF-2, induced after infection with tubercle bacilli, and CXCL8, induced in the presence of either stimuli." (PMID 37781389, 2023). "CXCL8 is broadly known as a potent neutrophil chemoattractant, able to promote the recruitment of neutrophils and other granulocytes to the site of infection." (PMID 36680273, 2023). "CXCL8 acts to recruit immune cells to the site of infection and has an important role in neovascularization, while TNFα is important to induce acute inflammation and is implicated in neutrophil survival/apoptosis." (PMID 36768864, 2023). "The chemokine (C-X-C motif) ligand 8 (CXCL8), in turn, participates in the activation and recruitment of neutrophils, which are important for the immune response against infection." (PMID 37999614, 2023). "On the contrary, other studies described increased serum levels of CXCL8 after infection with genotype II virulent isolates Armenia07, Armenia08 and SY18." (PMID 36680273, 2023). "Infection with NTHi is also associated with transcriptional upregulation of cytokines CCL2 (MCP1), TNF, IL-1β, IL-6, CXCL8 and alarmins (TSLP, IL-33 and IL-25)." (PMID 37180449, 2023). "Pre-infection of BM-DCs by one or both mycoplasmas induced, in general, similar levels of IL-6 and CXCL8 to those induced by S. suis alone." (PMID 37513713, 2023). "CXCL8 and IL-6 were also reported to increase in nasal aspirate after infection and show a strong correlation with symptoms." (PMID 36999069, 2023). "Further, patients with more severe symptoms during the early phase of infection had significantly higher CXCL8 expression in their serum when compared to WNV-negative controls." (PMID 36992514, 2023). "After 6 h infection with H. pylori, the secretion of IL-8 was increased as expected, and in parallel the expression of CXCL8 was also induced several times in both GES-1 and AGS cells (respectively)." (PMID 37894827, 2023). "In summary, our model shows elevated IL-1β, IL-6 and CXCL8 mRNA levels after 24 h infection with PA." (PMID 37432929, 2023). "Inflammatory chemokines (e.g. CXCL8) coordinate the directional chemotaxis of leukocytes to inflammatory sites (infection & tissue injury)." (PMID 36725964, 2023). "Compared with infection alone, H. influenzae and rhinovirus coexposure synergize with the respiratory epithelium to stimulate CXCL8 and CCL20 production, leading to more severe airway inflammation." (PMID 37305112, 2023). "CXCL8 is the most potent human neutrophil-attracting chemokine and plays crucial roles in the response to infection and tissue injury." (PMID 36725964, 2023). "While the levels of both mRNA and secreted protein for IL-1α and CXCL8 increased in response to infection, the levels of CXCL10 and CCL20 in the culture supernatant decreased." (PMID 37067432, 2023). "A set of inflammation-related genes, including CXCL8, was significantly increased after RV-A16 infection and even further (significantly) when combined with CS exposure compared to either exposures alone." (PMID 37612597, 2023). "Surprisingly, the gene for IL-8 (CXCL8), a chemokine, strongly associated with C. difficile infection was significantly downregulated at 3, 6, and 12 hours post-infection." (PMID 37615437, 2023). "NTHi significantly increased concentrations of IL-8 (CXCL8) in PBEC supernatants by 24 h post-infection, (2-way ANOVA with post hoc Sidaks)(3A)." (PMID 37180449, 2023).
infection (continued). "We have made relevant statistical analysis on CXCL8/9/10/11/13 in infection immunity, autoimmunity and inflammatory response of related organs, and found that it has no significant statistical significance in HNC." (PMID 35905218, 2022). "When comparing the levels of CXCL8/IL-8 in patients with a moderate clinical presentation of the infection, we noted a statistically significant elevation in concentrations in the plasma samples of patients infected with the Wuhan strain." (PMID 36012323, 2022). "Upon infection, the small intestinal epithelium secretes pro-inflammatory mediators, such as IL8 (CXCL8)." (PMID 35369438, 2022). "CXCL-8 is a chemoattractant produced by several types of cells to attract neutrophils and other defense cells to the infection site." (PMID 35602018, 2022). "Pro-inflammatory IL-8(CXCL8), regulatory IL-10 and TH-2 type IL-9 cytokines were measured in serum samples of AE patients and infection-free controls using specific ELISA." (PMID 35108275, 2022). "In the ex vivo organ culture (EVOC) model of ovine interdigital skin, infection with D. nodosus stimulated IL-1β release; however, CXCL8 levels increased in both infected and mock-infected explants." (PMID 36496756, 2022). "Various inflammatory cytokines such as TNF (TNF), some ILs (IL1α, IL1β), and chemokines (including CCL2, CCL4, CCL5, CXCL8) were significantly up-regulated under all observation points after YC-2020 infection." (PMID 36338035, 2022). "C-X-C Motif Chemokine Ligand 8 (CXCL8) is a major mediator of the inflammatory response, CXCL8 clears pathogens and protects the host from infection by attracting neutrophils and T cells." (PMID 36506032, 2022). "CXCL8/IL8 acts as a strong neutrophil chemoattractant to the site of infection and as a major proinflammatory cytokine." (PMID 36359162, 2022). "We analyzed IL-6 and TNF transcript level, as well as two other ARE-containing RNAs, encoding CXCL8 and COX-2 which were elevated after infection with SARS-CoV-2 and OC43." (PMID 35998203, 2022). "The transduction of CagA or infection with H. pylori downregulates KLF4 expression by inducing CXCL8 expression, and low KLF4 expression further upregulates CXCL8 expression." (PMID 35967444, 2022). "Neutrophils play a central role in innate immunity acting as the first line of host defense against infection, and CXCL8 activity is required for neutrophil migration and recruitment to inflamed sites during infection." (PMID 35958623, 2022). "The CXCL8 is a neutrophil chemoattractant which recruits the neutrophil at the site of infection and initiates a proinflammatory response mediated by the IL-8 and other cytokines." (PMID 36532041, 2022). "This chemokine is often recognized as one of the potential biomarkers of infection severity, although its role in the pathogenesis of SARS-CoV-2-induced infection is yet to be explored, since CXCL8/IL-8 is mostly associated with neutrophil trafficking." (PMID 36012323, 2022). "For example, both LSMMG and spaceflight infections upregulated inflammatory genes CXCL8 (IL-8) and PTGS2 (COX2) as well as IFIT1, a positive regulator of type I interferon signaling involved in limiting LPS-associated inflammation in human macrophages." (PMID 35711662, 2022). "Here we found that infection of EBV in PBMCs caused substantial downregulation of several chemokines, including CXCL16, CXCL8 and SIPR5 all of which play roles as mediators of the inflammatory response to many viruses." (PMID 36272970, 2022). "Neutrophils migrate to the infection site and mediate phagocytosis, degranulation, the release of NETs, secretion of chemokines and cytokines (CXCL8, TNFα), and ROS production." (PMID 35674675, 2022). "CXCL8 expression was significantly decreased following infection and was at least partially dependent on EGR1." (PMID 35746681, 2022).
infection (continued). "In another study using Cajal cells, the expression of CXCL8 was increased by the cp TC strain by more than 1000-fold, confirming that infection with the cp strain induced a significant response at the transcriptome level." (PMID 35746747, 2022). "LSECs and KuCs secrete CXCL8 in the liver in response to alarmins and infection attract immune cells so as to clear pathogens, cellular debris, alarmins, and metabolic waste restoring liver function." (PMID 36451225, 2022). "Conversely, CXCL8 from NT cells increased over time, and concentrations from Pa stimulated cells peaked at 12 hours post infection; the peak induction compared with NT was seen at eight hours post infection (31.0 fold (IQR, 12.6–47.7)." (PMID 33524056, 2021). "Metformin treated 5637 cells increased mRNA expression of the proinflammatory cytokines IL1B and CXCL-8 upon infection." (PMID 34584119, 2021). "It is known that epithelial cells secrete, among other cytokines and chemokines, MIP1 and CXCL8 that attract MPs and neutrophils to the site of infection." (PMID 34307535, 2021). "Of particular importance are the Pa-induced chemokine CXCL8, which is instrumental in neutrophil migration to the site of infection, and the cytokine IL-6, which is involved in the release of acute phase proteins and immune cell differentiation." (PMID 33524056, 2021). "Similar to F3 and IL23A expression, CXCL8 transcripts were observed at much greater intensity and in a much larger area of tissue in samples from WT vs ΔΔstx infection." (PMID 33529199, 2021). "For example, cytosolic focal adhesion kinase (FAK) was shown to be activated (phosphorylated) within 15 min of infection, well before the onset of adenoviral gene expression, and its chemical inhibition reduced CXCL8 expression." (PMID 34960773, 2021). "In the very early stage of infection, chemokines such as IL-8 (CXCL8), MCP-3 (CCL7), and RANTES (CCL5) are produced by numerous cell types." (PMID 33483611, 2021). "CXCL8, a chemotactic factor that guides neutrophils to the site of infection, was identified as the hub gene of BA in this study." (PMID 35111704, 2021). "Twelve coinfections induced less CXCL8 than infection with E. coli K-12 alone (mean reduction 45.7%, range 26–64%)." (PMID 34361936, 2021). "CXCL8 was highly expressed in all animals before infection; then, it transiently decreased on day 1 to 2, subsequently increased, and then returned to baseline (not shown)." (PMID 33671829, 2021). "Accordingly, gene expression analysis revealed an early and significant induction of IL1A, IL6, and CXCL8 expression during infection of keratinocytes with S. aureus accounting for the detrimental effects observed." (PMID 34944618, 2021). "The extracellular version of protein Nef expressed in the early phase of infection of the human immunodeficiency virus (HIV) triggered the release of CXCL8/IL-8 and CCL3/MIP-1α through the CXCR4 receptor in MCs." (PMID 34211473, 2021). "The induction of CXCL8 by Leishmania has also been demonstrated in a murine model and in human infections." (PMID 34832536, 2021). "Twelve coinfections induced less CXCL8 than monomicrobial infections (mean reduction 39.3%, range 7–64%)." (PMID 34361936, 2021). "Human neutrophils produce CXCL8 upon exposure to Leishmania major and Leishmania infantum species, increasing the early recruitment of neutrophils to sites of infection." (PMID 34607465, 2021). "The rapid recruitment of neutrophils to injury or infection sites is mediated by IL-8, also known as CXCL8 (a chemokine produced by macrophages and endothelial cells)." (PMID 34358055, 2021). "The optimal infection period was also investigated, with assessment of Pa-induced IL-6 and CXCL8 at 2, 4, 8, 12 and 24 hours post infection." (PMID 33524056, 2021). "A member of the CXC chemokine family, Il8/Cxcl8, regulated by Il1b, functions as a chemotactic factor by recruiting specific subsets of leukocytes to sites of inflammation and infection." (PMID 35035387, 2021).
infection (continued). "Primarily CXCL8 encourages neutrophil migration to the liver, where they promote phagocytosis to clear the infection." (PMID 33117329, 2020). "During the process of inflammation, CXCL8 recruits leukocytes to the site of infection, ultimately resulting in increased neutrophil infiltration, which is responsible for the damage of endothelial cells." (PMID 32766720, 2020). "The extensive secretion of neutrophil chemoattractant CXCL8 (IL-8) has been found to occur during the infection with hRSV as early as 2 h.p.i. and to be steadily secreted for as long as 6 d.p.i.." (PMID 32545470, 2020). "CXCR1 and its ligand C-X-C motif chemokine ligand 8 (CXCL8)/interleukin 8 (IL-8) have been reported in multiple fish species and fish CXCL8/IL-8 is also induced in spleen upon infection with VHSV and IHNV." (PMID 32986779, 2020). "In particular, the up-regulation in CXCL8 expression is a remarkable effect of the combined hormones during infection, and it would be interesting to analyze in further research if leukocyte chemotaxis is induced under these conditions." (PMID 32605209, 2020). "To validate these findings in mice, we infected primary HUVEC cultures with different doses of O. tsutsugamushi (3 and 10 MOI) and found a dose-dependent increase in ICAM1 and IL8/CXCL8 transcripts at 24 h post-infection." (PMID 32119672, 2020). "CXCL8 is a chemotactic cytokine that is produced by various cell types to stimulate the recruitment and activation of neutrophils to infection and inflammatory sites." (PMID 32260212, 2020). "Strikingly, this was associated with a reduced T cell capacity to produce CXCL8, highlighting the CXCL8 pathway as a potential therapeutic target for preventing infection in preterm babies." (PMID 32152273, 2020). "Human metapneumovirus (hMPV), which is closely related to RSV, has been associated with the release of IL-6,CXCL8,CXCL10, RANTES, CCL2, CCL3 and CCL20 from airway epithelial cells following infection in vitro." (PMID 31331089, 2019). "While CXCL8/IL8 attracts neutrophils, basophils and T-cells to the site of the infection, CXCL10 is chemotactic for monocytes and T-lymphocytes by binding to CXCR3." (PMID 31619718, 2019). "Teleost CXCR1 and CXCR2 are conserved receptors for interleukin-8 (IL-8, also termed CXCL8) and are important for the regulation of neutrophil recruitment and migration to sites of infection and injury." (PMID 30837998, 2019). "A similar role for DUSP1 was seen in infection of the NCI-H1299 cell line with the avian coronavirus infectious bronchitis virus, with DUSP1 siRNA treatment increasing mRNA levels of CXCL8 in response to infection." (PMID 30764493, 2019). "Evidence of this process was observed during the infection with T. rubrum as CXCL8 gene expression was increased in tissue, showing attempts to attract immune cells to the damaged tissue." (PMID 31231322, 2019). "Its structural homologue in S. pyogenes, SpyCEP, inactivates CXCL8 and impairs the recruitment of neutrophils to the site of infection." (PMID 31212697, 2019). "One study showed weaker production and release of CXCL8 in response to infection with two strains of rhinovirus in primary bronchial epithelial cells treated with the JNK inhibitor SP600125." (PMID 30764493, 2019). "In vitro endothelial cells respond to infection with C. albicans by secreting TNFα, which stimulates CXCL8/IL-8 and E-selectin expression by an autocrine mechanism." (PMID 30934602, 2019). "Macrophages and both epithelial and endothelial cells produce CXCL8 in response to infection or injury." (PMID 30766892, 2019). "Recent work has furthered this knowledge, showing reduced production of CXCL8 by primary bronchial epithelial cells when p38 signaling was inhibited prior to infection with rhinovirus." (PMID 30764493, 2019). "Infection of this cell line with the hRSV Long strain showed an increase in the transcript levels for CXCL8 at 4 h post-infection, which was observed up to 24 h post-infection." (PMID 30936869, 2019).
infection (continued). "CXCL8 is a chemokine that recruits neutrophils to the site of infection, whereas IL-1α was shown to be induced in the skin by commensals where it substantially contributes to skin immunity." (PMID 31227691, 2019). "There was a statistically significant increase in the expression of IL-8/CXCL8 after infection with ZIKV and JEV, again with donor I expressing the highest levels." (PMID 31057517, 2019). "In accordance with previous results, infection of PBECs with RV14 led to a small increase in CXCL8 release which was unaffected by DUSP10 knockdown." (PMID 30333178, 2019). "CXCL8 production increases during infections and in response to LPS and pro-inflammatory cytokines (TNF and IL-1)." (PMID 31188820, 2019). "SpyCEP is highly expressed in vivo and cleaves CXC chemokines, including CXCL1, CXCL2, CXCL3, CXCL5, CXCL6, and CXCL8, which results in an impaired chemoattraction of eosinophils, neutrophils, and monocytes to the site of infection." (PMID 31212697, 2019). "Through the secretion of CXCL8, macrophages recruit and activate other immune cells such as neutrophils, monocytes and lymphocytes to respond to infection, disease or injury." (PMID 30969964, 2019). "A study of the effect of the ketone body BHB on innate defense capability of the bovine mammary epithelial cells showed that expression of this gene (CXCL8) was significantly induced 30 h post infection with E. coli bacteria." (PMID 31311492, 2019). "CXCL8 is a chemokine that recruits neutrophils to the site of infection, whereas IL‐6 is an important proinflammatory cytokine and an important mediator in acute inflammation." (PMID 29536668, 2018). "SpyCEP is a 170 kDa serine protease expressed on the surface of GAS, which proteolytically cleaves and abrogates the activities of the human chemokines CXCL1, CXCL2, CXCL6, and CXCL8/IL-8, impairing neutrophil recruitment to the site of infection." (PMID 29868516, 2018). "Some studies have demonstrated the role of the flagellin of P. aeruginosa in induction of IL-6 and TNFα or CXCL8 during mouse infections." (PMID 30070169, 2018). "The most prominently induced genes included IL1B and IL8 (CXCL8), which were upregulated in all isolated cell types after infection of the lung tissue." (PMID 29977236, 2018). "In contrast, S. aureus 6850 infection alone resulted in a marginal induction of these cytokines and chemokines, while IL-1β and CXCL8 mRNA levels were elevated after bacterial infection." (PMID 28195157, 2017). "CLEC9A-mediated SYK activation specifically promotes the production of CXCL8 and IL-1β, which are central to neutrophil recruitment and activation during the early stage of infection." (PMID 29065139, 2017). "Mock-infected controls and infected skin explants released similar concentrations of CXCL8 in the culture media that were accumulated between 0–4 h, 4–16 h and 16–28h post infection." (PMID 28959685, 2017). "Chemokine CXCL8 plays a pivotal role in host immune response by recruiting neutrophils to the infection site." (PMID 29118271, 2017). "DCs also secrete tumor necrosis factor (TNF)-α and the chemokine CXCL8 which recruit neutrophils to the infection site." (PMID 29358941, 2017). "In the present study, our results indicate that ALF fragments modulate neutrophils by limiting their IL-8 (CXCL-8) production, an important mediator involved in neutrophil recruitment to the infection site." (PMID 28373877, 2017). "During infection, CXCL8 is up-regulated at the site of inflammation, allowing the immune system to direct PMN in inflamed tissues via CD182." (PMID 27802348, 2016). "Central to the recruitment of these neutrophils to the site of infection is the secretion of the chemokine CXCL8 by host cells." (PMID 27002636, 2016). "We observed the levels of expression of previously reported cytokines such as IL6, and CXCL8 (IL8) increase between 4 and 7 days post-infection." (PMID 27595844, 2016).